IFIT3 (interferon induced protein with tetratricopeptide repeats 3)
Diseases named in the same sentence as IFIT3 in open-access papers (continued):
Sharing a sentence is not in itself a finding about the gene and the disease.
tumor (continued). "After labeling IFIT3 with the STrEP Tag, protein complexes that formed after interaction of IFIT3-StrEP with proteins from the tumor cell lysate stained positive for JNK and STAT1 by Western Blot analysis, while other typical signaling proteins such as Akt, EGFR, MAPK and Src were not detectable." (PMID 25650658, 2015). "Thus, targeting IFIT3 or its downstream effectors may serve as a therapeutic strategy to restore anti-tumor immunity and enhance the efficacy of immune checkpoint inhibitors, making IFIT3 a promising target for cancer immunotherapy." (PMID 40061935, 2025). "Thus, targeting IFIT3 within the TME may offer novel strategies to reprogram the immune landscape toward tumor clearance." (PMID 40061935, 2025). "In addition, IFIT3 modulates pro-inflammatory macrophages, amplifying the expression of pro-inflammatory cytokines and exacerbating inflammation, which fosters a microenvironment favorable to tumor growth." (PMID 40061935, 2025). "In summary, combining IFIT3-targeted therapies with existing immunotherapies (e.g., immune checkpoint inhibitors or radiotherapy in combination with immunotherapy) may provide a synergistic approach to overcoming tumor immune resistance." (PMID 40061935, 2025). "Therefore, the decreased expression of circ_BBS9 and IFIT3 in LUAD may impact tumor immunity and contribute to tumorigenesis, providing important insights for future immunotherapy research." (PMID 39139574, 2024). "Additionally, IFIT3 exhibits differential expression across various tumor tissues." (PMID 39139574, 2024). "In particular, increased IFIT1 and IFIT3 expression has been correlated with improved therapeutic response to chemotherapeutics and immunostimulating agents and increased IFIT2 expression in the tumour tissues of patients was associated with improved patient survival." (PMID 36579897, 2023). "In particular, IFIT3 enhances NF-κB activity, which subsequently promotes the secretion of inflammatory mediators such as IL-6, TNF-α, and COX-2, driving tumor cell proliferation, resistance to apoptosis, and angiogenesis." (PMID 40061935, 2025). "For instance, IFIT1, IFIT3, IFI-16, ISG15, MX1, and OAS1 have been shown to have tumor-suppressive function." (PMID 40563638, 2025). "IFIT3 overexpression has been identified as a major contributor to epithelial-mesenchymal transition (EMT) in OSCC, where it promotes tumor invasiveness." (PMID 40061935, 2025). "High expression of IFIT3 was found in HNSC; it was also significantly highly expressed in 44 cases of HNSC tumor than matched adjacent normal tissue samples (P < 0.0001)." (PMID 38273364, 2024). "Western blot analysis of tumor tissues showed that COL8A1 knockdown reduced IFIT1 and IFIT3 expression, as well as EGFR phosphorylation." (PMID 35280763, 2022). "We observed similar correlations of the expression level of STAT1 and IFIT3 with activated dendritic cells, activated NK cells, CD8 T cells and memory activated CD4 T cells, which were representative cells for anti-tumor immunity estimated by the CIBERSORT." (PMID 36311733, 2022). "We found ACAP1, IFIT3 and TAP1 were upregulated in tumor samples, while ADAMTS9, COL6A2, FBN1 and FSTL1 were downregulated in tumor specimens." (PMID 34112144, 2021). "Conversely, silencing IFIT3 and PLSCR1 genes in tumor cells can negatively affect the internalization of vesicular stomatitis and Newcastle disease viruses." (PMID 34771433, 2021). "A number of interferon-stimulated genes (ISGs) were found to be highly induced in tumor compared to non-tumor samples, such as GBP1, CAMP, PTGS2, GOLIM4, IFIT3, MX1, LTF, and CYBB." (PMID 34400640, 2021). "First, we observed the up-regulation of IFIT3 in our PDAC cell line L3.6pl and the patient-derived primary tumor cell line TBO368 after gemcitabine treatment at both the mRNA and protein level." (PMID 32641986, 2020).
tumor (continued). "Among the top genes differentially expressed between sensitive and resistant cells, we identified a group of candidates related to tumor-microenvironment response (CCL5, CXCL10, IFIT3, IFI44, IFNL2)." (PMID 32365528, 2020). "Although IFIT2 belongs to the same family, it executes tumor suppressor functions, whereas IFIT1 and IFIT3 have tumor-promoting properties in OSCC." (PMID 31921891, 2019). "IFIT1 and IFIT3 promoted EGFR activation in OSCC cells and enhanced the tumor-preventive activity of gefitinib." (PMID 31921891, 2019). "IFIT-silenced and control tumor cell lines were generated by simultaneously transducing tumor cells with IFIT1, IFIT2 and IFIT3 small hairpin RNAs (shRNA) or with scrambled shRNA, respectively." (PMID 28878208, 2017). "We also demonstrate for the first time that HSP90 inhibition upregulates interferon response genes in the tumor, notably IFIT1, IFIT2 and IFIT3, both in vitro and in vivo." (PMID 28878208, 2017). "In addition to regulating immune cell infiltration and polarization, IFIT3 is also involved in mediating the inflammatory responses within the TME, which play a key role in tumor progression." (PMID 40061935, 2025). "We observed that IFIT3 is under-expressed in LUAD and increases with tumor grade." (PMID 39139574, 2024). "T cells were found to be localizing selectively around a distinct malignant duct located center-left of the tissue section, with attributed genes such as immune checkpoint costimulatory receptor CD28, as well as IFIT3, CCL5, and PLAAT4 implicating an active anti-tumor immune response." (PMID 36906603, 2023). "The increased transcripts for EGR1, interferon-induced proteins (IFI6, IFIT1, IFIT3, IFIT5), and MHC class II (HLA-DRA) indicated strong stimulation of IFN signaling, which could result in activation of macrophages in the tumor microenvironment." (PMID 37834191, 2023). "The results from MMTV-PyVT mice show that TPPP3+ monocytes, ISG15+ macrophages, IFIT3+ neutrophils, and IL12B+ DCs are mainly present in the tumor-reprogrammed lung microenvironment, and the metastasis-associated myeloid subpopulations are validated at the protein level." (PMID 37483625, 2023). "To further investigate whether COL8A1-mediated tumor progression required IFIT1 and IFIT3 knockdown, we examined cell proliferation in COL8A1-overexpressing and IFIT1/IFIT3-silenced NSCLC cells." (PMID 35280763, 2022). "Owing to an upregulation of interferon-inducible genes, including Ifit1, Ifit3 and Bst2, the EO771 and EO771.LMB tumours might correspond more closely to the interferon-rich subtype of human basal-like tumours." (PMID 25633981, 2015). "Indeed, heterogeneous IFIT3 expression was observed in 16.4% of tumor specimens and no survival benefit for patients with tumors that expressed low IFIT3 levels was reported, with heterogeneity considered one of the potential explanations of divergent results." (PMID 40564154, 2025). "Second, tumor subsets enriched for microenvironment features, including hypoxia markers (e.g., Slc2a1, Pdk1, Car9), extracellular matrix (ECM) genes (e.g., Matn2, Fn1, Dcn, Col6a1), vasculature (e.g., Cdh5, Pecam1, Vwf), and interferon response genes (e.g., Rsad2, Ifit3, Gbp3, Cxcl10, Cd274)." (PMID 40171265, 2025). "Likewise, interferon response genes (including TLR3, MX1, RSAD2, IFI44, IFI27, IFIT1, and IFIT3), and chemokine genes (including CCL7, CXCL10, CXCR1, and CCL25) were significantly increased in PM-treated MM tumor tissues, whereas panobinostat showed minimal effects at equivalent doses." (PMID 40562746, 2025). "In order to investigate the relationship between IFIT3 expression and clinicopathological features of HNSC patients, we performed IHC analysis to detect the IFIT3 expression on the HNSC tissue microarray containing 101 tumor tissues and 57 adjacent normal tissues." (PMID 38273364, 2024).
tumor (continued). "Then, we performed immunofluorescence staining on the normal lung, primary tumor, and metastatic lung sections using the markers of Tppp3+ monocytes (LY6C and TPPP3), Isg15+ macrophages (F4/80 and ISG15), Ifit3+ neutrophils (MPO and IFIT3), and Il12b+ DCs (CD11c and IL12B)." (PMID 37483625, 2023). "The direct association of IFIT1 or IFIT3 with heat shock proteins (Hsp90α/β) suggests a unique mechanism of action of IFIT1 and IFIT3 that may be involved in activating Hsp90 and several of its downstream signaling regulators, which are crucial for OSCC tumor progression and drug resistance." (PMID 31921891, 2019). "By contrast, tumor-associated CD4+ T cells projected mostly onto resting blood and tissue T cells, while CD4+ T cell activation states and associated markers (NME1, IFIT3) were largely absent." (PMID 31624246, 2019). "Furthermore, simultaneous knockdown of IFIT3 and UBE2O did not significantly affect the subcutaneous tumor volume compared with that in the control group; however, knockdown of UBE2O alone resulted in a significant reduction in tumor volume (p < 0.001)." (PMID 38129382, 2023).
cancer (46 papers, 2015 to 2025). A tumor composed of atypical neoplastic, often pleomorphic cells that invade other tissues. "In ESCC, low versus high expression of IFIT3 in cancer tissues was associated with prolonged DFS and overall survival." (PMID 40564154, 2025). "Furthermore, in this cancer, IFIT3 expression was positively associated with increased resistance to chemotherapeutics, such as gemcitabine, 5-FU and irinotecan, through various pathways." (PMID 40564154, 2025). "These correlations with multiple immune subsets suggest the function of IFIT3 might be associated with the cancer microenvironment and immune system." (PMID 33711033, 2021). "However, the enhanced expression of IFIT3 in pancreatic cancer has been shown to cause pseudo-inflammation and result in cancer progression." (PMID 31921891, 2019). "IFIT3 expression might also be associated with the location of the first relapse, as patients with the first recurrence in the lungs survived longer and showed low IFIT3 expression in cancer tissues." (PMID 40564154, 2025). "However, depending on the cancer type, IFIT3 expression might be associated with unfavorable or favorable clinical outcomes." (PMID 40564154, 2025). "In that study, IFIT3 silencing was shown to inhibit HCC cell migration and attenuate aggressiveness via complex regulation involving cancer associated fibroblasts-mediated secretion of CXCL11 and circular and micro RNAs." (PMID 40564154, 2025). "This review provides a comprehensive overview of IFIT3’s multifaceted roles in cancer progression, immune evasion, and drug resistance." (PMID 40061935, 2025). "The IFIT3 gene exhibits significant expression variations across a wide range of cancer types, playing a crucial biological role." (PMID 40061935, 2025). "Future research should focus on uncovering IFIT3’s interactions with additional immune checkpoints across various cancer types and investigating the efficacy of IFIT3-targeted therapies in clinical settings." (PMID 40061935, 2025). "Integrating IFIT3-targeted therapies with established immunotherapies, such as PD-1/PD-L1 inhibitors, holds promise for novel cancer treatment strategies." (PMID 40061935, 2025). "Future studies should explore more deeply the regulatory role of IFIT3 in other immune checkpoint molecules, especially the differential expression in different cancer types." (PMID 40061935, 2025). "Given its diverse biological functions, IFIT3 has emerged as a promising target in cancer immunotherapy." (PMID 40061935, 2025). "GSEA analysis of two groups revealed that the different expression genes in IFIT3 high-expression group were significant overlaps in pathways in cancer and EMT-related genes." (PMID 38273364, 2024). "CCK-8 assays, colony formation assays, wound-healing assays, transwell assays, and sphere formation were used to explore proliferative, migratory, and invasive activities and cancer stemness of HNSC cells after IFIT3 knockdown and over-expressed." (PMID 38273364, 2024). "We then plotted the expression profile of the top four upregulated ISGs (IFIT2, ISG15, IFIT1 and IFIT3) among various cancer types from the TCGA database." (PMID 38926796, 2024). "All of these findings support the potential of IFIT3 as a marker or target for distinguishing malignant tumors." (PMID 39139574, 2024). "IFIT3 plays crucial role in antiviral innate immunity and has been involved in cell proliferation, apoptosis, differentiation, and cancer development." (PMID 38273364, 2024). "Cancer cells recruited the CD4_T_cells_c2_CXCL13, CD8_T_cells_c1_GZMK, CD8_T_cells_c4_IFIT3, NK_cells_KLRD1, and Treg_cells_FOXP3 clusters through the CXCL10‐CXCR3 ligand–receptor pair." (PMID 36529697, 2023). "Functional studies with IFIT proteins (IFIT1 and IFIT3) on various molecular signaling mechanisms implicates them in cancer progression and metastasis." (PMID 36766731, 2023).
cancer (continued). "The results of RT-qPCR verified that KU55933 significantly upregulated additional ISGs including ISG20, DDX58, DDX60, CCL5, and IFIT3 in CDDP-R cancer cells." (PMID 37174688, 2023). "The results showed that high expressions of ISG15, IFI27, OASL, CCL5, ISG20, IFIT3, and other 21 ISGs were significantly correlated with improved OS rates in cancer patients receiving ICB therapy." (PMID 37174688, 2023). "IFIT3 is a protein well known for being an antiviral effector, but recently its role in cancer has also been elucidated." (PMID 34622927, 2021). "Overall, this study sheds light on the previously unappreciated role of IFIT3 in regulating sEV protein content in PrCa cells and in intercellular communication in cancer progression." (PMID 34622927, 2021). "Because A549 cells are aneuploid cancer cells, we wished to examine the effect of IFIT3 and TRIM25 on Ad replication in normal human cells." (PMID 34724821, 2021). "Aside from its antiviral activity, the role of IFIT3 in cancer is poorly understood, and even less so in PrCa." (PMID 34622927, 2021). "Notwithstanding, little is known regarding IFIT3 expression or its potential role in sEVs derived from cancer cells." (PMID 34622927, 2021). "Notwithstanding, our findings are consistent with other research supporting an anti-proliferative role of IFIT3 in cancer, as we demonstrate a new role for the αvβ6 integrin as a negative regulator of IFIT3." (PMID 34622927, 2021). "Increased expression of IFIT1 and IFIT3 genes was observed in DNA damage-resistant sublines compared to parental cell lines in various cancers, including OSCC cells." (PMID 31921891, 2019). "This suggests that the relative baseline level of IFIT3 mRNA allows prediction of the sensitivity of cancer cells to the influence of innate immune modulators." (PMID 29986702, 2018). "It has been reported that IFIT3 is a proto-oncogene, and its upregulation can maintain the cellular condition of pseudo inflammatory in cancer tissue." (PMID 29301256, 2018). "Elevated level of IFIT3 in cancer cells can be regarded as alteration in activation pathways as well as known IFIT3-dependent downstream signalling." (PMID 29986702, 2018). "Summarizing our results and recently reported data, IFIT3 expression can be considered a prognostic indicator of the efficacy of cancer immunotherapy." (PMID 29986702, 2018). "It should be noted that the IFIT3 level can be used as an indicator of cancer cells with null or low sensitivity to immune-stimulating agents." (PMID 29986702, 2018). "With ongoing research, the role of IFIT3 in cancer has become increasingly prominent." (PMID 40061935, 2025). "In contrast, in NSCLC, a report suggests that IFIT3 might, however, act to promote cancer progression via its upregulation by COL8A1 and subsequent mediation of EGFR activation, a major factor in pathogenesis of this disease." (PMID 40564154, 2025). "However, the effects of IFIT3 on cancer, particularly in HNSC, and its molecular mechanisms remain undefined." (PMID 38273364, 2024). "Although prior research has indicated the potential impact of immune infiltration on the behavior and prognosis of cancer patients, the mechanism of interaction between IFIT3 and the TME remains unclear." (PMID 39139574, 2024). "Interestingly, IFIT1 and IFIT3 genes are upregulated during cancer metastasis and invasion and mediate their growth-promoting actions by complexing and phosphorylating Hsp90 and its client proteins, including PKC, EGFR, Akt, and p38." (PMID 36766731, 2023). "Indeed, studies involving IFIT protein (IFIT1, IFIT3) functions and their participation in various molecular signaling mechanisms implicates them in cancer progression and metastasis." (PMID 36230929, 2022). "Similarly, the altered frequencies of STAT1 and IFIT3 came second and fourth among 525 samples from the pan-cancer TCGA cohort." (PMID 36311733, 2022).